MUC5B (mucin 5B, oligomeric mucus/gel-forming)
Diseases named in the same sentence as MUC5B in open-access papers (continued):
Sharing a sentence is not in itself a finding about the gene and the disease.
ovarian carcinoma (4 papers, 2005 to 2025). A malignant neoplasm originating from the surface ovarian epithelium. "Ju et al27 also showed that MUC5B was a down‐regulated gene in chemotherapy resistant epithelial ovarian cancer." (PMID 32441484, 2020). "We will further study the interaction between JUND/JUNB and MUC5B in vivo and in vitro to uncover the mechanism of chemotherapy sensitivity in ovarian cancer." (PMID 32441484, 2020). "The kallikreins have been shown to be potentially useful prognostic markers in ovarian cancer and laminin γ2 and MUC5B were shown to display high expression among some of the cancers at the protein level as well, using Western analyses." (PMID 16042759, 2005). "Additionally, in ovarian cancer, MUC5B contributes to chemoresistance via modulation of the NF-κB pathway." (PMID 41409294, 2025).
Pneumocystis infection (4 papers, 2019 to 2024). "However, mucus progression, expression of MUC5B essential for airway defense, and potential for pharmacologic modulation of mucus during Pneumocystis infection remain unknown." (PMID 30765827, 2019). "The increase in distal airway mucins during Pneumocystis infection is related to colocalization of CC10 with Muc5b and independent of mitosis, which suggests cellular transdifferentiation process." (PMID 31170201, 2019). "No studies of MUC5B expression in infant lungs or of the murine homolog gene Muc5b during Pneumocystis infection are available." (PMID 30765827, 2019). "Induction of the CLCA1 pathway with increased mucins has been shown to correlate with Pneumocystis infection in humans and in animal models and is strongly related to IL-13 driven mucus cell metaplasia, STAT6 activation and MUC5AC and MUC5B expression in the airways." (PMID 31333624, 2019).
pneumonia (4 papers, 2014 to 2022). An acute, acute and chronic, or chronic inflammation focally or diffusely affecting the lung parenchyma, caused by an infection in one or both of the lungs (by bacteria, viruses, fungi, or mycoplasma.). "Our findings revealed that MUC5B rs35705950 is strongly linked to an increased risk of pneumonia diseases in the Asian and Caucasian populations." (PMID 32252656, 2020). "Herein, we collected currently published data to comprehensively evaluate the impact of the FCGR2A (Fc fragment of IgG receptor IIa) rs1801274 and MUC5B (mucin 5B, oligomeric mucus/gel-forming) rs35705950 variations on susceptibility to pneumonia diseases." (PMID 32252656, 2020). "We observed a positive association between MUC5B rs35705950 and the overall risk of pneumonia in the Asian population." (PMID 32252656, 2020). "It is possible that the “T” allele of MUC5B rs35705950 confers an enhanced susceptibility to pneumonia patients in a dose-dependent manner." (PMID 32252656, 2020). "Therefore, we performed an updated meta-analysis to comprehensively assess the effect of MUC5B rs35705950 on the risk of overall pneumonia disease based on available case-control studies as of February 2020." (PMID 32252656, 2020). "FCGR2A rs1801274 and MUC5B rs35705950 were selected due to the research status of pneumonia-related variations and the novelty of the data analysis." (PMID 32252656, 2020). "Our study enables readers to understand the current research status of pneumonia-related MUC5B rs35705950 in different populations, as well as the pooling evidence based on the currently available data." (PMID 32252656, 2020). "However, only ten studies were included, and the genetic association between MUC5B rs35705950 and the susceptibility to other pneumonia types has not yet been investigated." (PMID 32252656, 2020). "After database retrieval and publication selection, we excluded reports of potential pneumonia-associated gene variation without enough or updated data, and finally focused on two variants, namely, FCGR2A rs1801274 and MUC5B rs35705950." (PMID 32252656, 2020).
airway hyperresponsiveness (3 papers, 2018 to 2025). "In inflamed airways, MUC5B contributes to honeycomb-like structures and plays a role in mucociliary transport, whereas MUC5AC is associated with mucus plug formation and airway hyperresponsiveness." (PMID 40869396, 2025). "Muc5b has physiologic functions, ensuring normal mucus clearance, whereas Muc5ac plays a role in mechanisms of allergen-induced airway hyperresponsiveness, mucous metaplasia, and airway mucus plugging." (PMID 29614747, 2018).
antisynthetase syndrome (3 papers, 2020 to 2024). Antisynthetase (AS) syndrome is a clinically heterogeneous form of idiopathic inflammatory myopathy characterized by myositis, arthralgia, Raynaud phenomenon, mechanic hands, interstitial lung disease (ILD), and serum autoantibodies to aminoacyl transfer RNA synthetases (anti-ARS). "Due to this, we evaluated the implication of MUC5B rs35705950 in antisynthetase syndrome (ASSD), a pathology characterised by a high ILD incidence." (PMID 31996780, 2020).
diabetes (3 papers, 2017 to 2021). "In a model that adjusted for sex, age and BMI, we observed significantly higher MUC5B expression in the group with T2D compared to those without diabetes (p-value = 0.00005)." (PMID 28346466, 2017).
head and neck cancer (3 papers, 2012 to 2021). A primary or metastatic malignant neoplasm affecting the head and neck. "The aim of the study was therefore to determine over time changes of total protein and IgA as well as mucin type O-linked glycans (mostly MUC5B and MUC7) in stimulated whole saliva in relation to dry mouth and sticky saliva in head and neck cancer patients." (PMID 34627217, 2021). "We investigated if MUC5B levels in SMG saliva could distinguish between the presence or absence of severe dry mouth complaints 12 months after radiotherapy (RT) for head-and-neck cancer (HNC)." (PMID 22704532, 2012).
influenza (3 papers, 2020 to 2022). An acute viral infection of the respiratory tract, occurring in isolated cases, in epidemics, or in pandemics; it is caused by serologically different strains of viruses (influenzaviruses) designated A, B, and C, has a 3-day incubation period, and usually lasts for 3 to 10 days. "IgA and MUC5B are known as the primary glycoproteins in human saliva, which can exert high anti-influenza activity through their sialylated glycochains." (PMID 35807530, 2022). "Given that both of the MUC5B and IgA are primary glycoproteins in human saliva with high anti-influenza activity, their protein and sialylation levels were further tested using Western blotting analysis and ELISA based MAL-II/SNA binding assay." (PMID 35807530, 2022).
Obesity (3 papers, 2017 to 2025). Accumulation of substantial excess body fat. "The combined alterations in IL-6, Ca2+, sAA, MUC5B and cortisol indicate a potential salivary biomarker pattern associated with obesity, underscoring the value of a multi-biomarker strategy for metabolic risk profiling." (PMID 41584074, 2025). "In conclusion, this study highlights IL-6, Ca2+, sAA, MUC5B and cortisol as a potential salivary biomarker-combination associated with obesity." (PMID 41584074, 2025). "Individuals with obesity showed significant lower Ca2+ levels, with a large effect (r = 0.8), as well as lower sAA (r = 0.3) and MUC5B levels (r = 0.7), both reflecting medium to large effects." (PMID 41584074, 2025). "Although individuals with obesity showed lower MUC5B levels with large effect size, this study cannot determine whether this reflects changes in glandular secretion, mucin glycosylation, or microbiome-mediated degradation." (PMID 41584074, 2025).
prostate carcinoma (3 papers, 2004 to 2025). A carcinoma that arises from epithelial cells of the prostate gland. "Comparing the mutations in pre- and post- resistant samples, we also fund that MUC7 and MUC5B mutation repair may be associated with longer PFS and ZNF91 mutation may be a key factor contributing to the development of drug resistance in prostate cancer." (PMID 37726835, 2023). "The loss of hormone dependence in this prostate cancer xenograft model is therefore marked by irreversible histological alterations, mucinous or neuro-endocrine, associated with an expression of secretory MUC2, MUC5B and MUC6, independent of the histological differentiation subtype." (PMID 14760390, 2004).
respiratory failure (3 papers, 2019 to 2020). The significant impairment of gas exchange within the lungs resulting in hypoxia, hypercarbia, or both, to the extent that organ tissue perfusion is severely compromised. "Mice with conditional lung deletion of one or two Muc5b alleles, termed Muc5blung ko, developed respiratory failure (P<0.0001)." (PMID 31699684, 2019). "The frequency of respiratory failure was increased when CCSP-Cre:Muc5b-floxed mice were between 20 and 30 weeks old with a higher probability in mice that carried the two mutated alleles (65% versus 35% for a single mutated allele)." (PMID 31699684, 2019).
type 2 diabetes (3 papers, 2017 to 2025). "Allele Counts by type 2 diabetes status for variants in the MUC5B and ABCC12 genes." (PMID 28346466, 2017). "Interestingly, genetic variants of Muc5b have been associated with type 2 diabetes." (PMID 41146523, 2025).
AIDS (2 papers, 2006 to 2010). A syndrome resulting from the acquired deficiency of cellular immunity caused by the human immunodeficiency virus (HIV). "With this in mind, we decided to investigate whether MUC5B and MUC7 from saliva of HIV patients or with full blown AIDS had a similar inhibitory activity, as the MUC5B and MUC7 from HIV negative individuals, against the virus." (PMID 20946627, 2010). "The purpose of this subsequent study was to investigate whether MUC5B and MUC7 from saliva of HIV patients or with full blown AIDS had a similar inhibitory activity against the virus." (PMID 20946627, 2010).
breast tumor (2 papers, 2012 to 2019). "To analyze the role of MUC5B in breast tumorigenesis, we transfected the MCF7 luminal breast tumor cell line with a plasmid encoding a mini-MUC5B mucin made of large composite unit of MUC5B with many O-glycosylated sites and flanked by two CYS domains." (PMID 23056409, 2012). "Moreover, MUC5B silencing was shown to reduce chemo-resistance of breast tumor cells, suggesting this as an interesting target also for LUAD, where we found MUC5B as one of the up-regulated genes." (PMID 31429720, 2019).
cervical tumors (2 papers, 2005 to 2014). "Increased expression of MUC5B in endometrial tumors but not in cervical tumors." (PMID 28250389, 2014). "In contrast, only MUC1 levels increased with no significant changes in expression of MUC5B and MUC8 in cervical tumors over normal cervical tissues." (PMID 16188033, 2005).
chronic otitis media (2 papers, 2019 to 2024). Chronic form of otitis media (disease). "The middle ear epithelium of chronic otitis media patients expresses MUC5B." (PMID 31814835, 2019).
colitis (2 papers, 2022 to 2025). Inflammation of the colon. "It has been shown that administration of the GLP‐1 receptor agonist liraglutide to a mouse colitis model induced transcriptional upregulation of the genes Ccl20, Il33 and Muc5b in Brunner's glands, which alleviated colitis." (PMID 41146523, 2025).
colorectal tumors (2 papers, 2009 to 2021). "High expression of the MUC5B gene was observed in poorly differentiated tumors compared to moderately and well-differentiated colorectal tumors, showing a statistically significant difference (P=0.033, Figure-6B)." (PMID 35572847, 2021). "Perhaps consistent with the requirement for Sox2 in goblet cell differentiation, Sox2 activated a Muc5AC-luciferase reporter in colorectal tumors, and Muc5B mRNA was increased in lung when Sox2 was overexpressed in a transgenic mouse model." (PMID 20011520, 2009).
Crohn disease (2 papers, 2015 to 2022). A gastrointestinal disorder characterized by chronic inflammation involving all layers of the intestinal wall, noncaseating granulomas affecting the intestinal wall and regional lymph nodes, and transmural fibrosis. "Reduced expression levels of several mucin genes, including MUC3, MUC4, and MUC5B in patients with Crohn’s disease, suggest primary or early mucosal defect of these genes." (PMID 35038288, 2022). "In Crohn ́s disease, MUC5AC expression is known to be induced in the intestine together with MUC5B and MUC6." (PMID 26162072, 2015).
endometrial adenocarcinomas (2 papers, 2005 to 2012). "Statistically, higher levels of MUC1, MUC5B and MUC8 were observed in endometrial adenocarcinomas compared to normal tissues." (PMID 16188033, 2005). "One significant conclusion that can be drawn from this study is that mucin genes, MUC1, MUC5B and MUC8 are all up-regulated in endometrial adenocarcinomas." (PMID 16188033, 2005).
Endometrial tumors (2 papers, 2005 to 2014). "Expression of MUC5B followed a similar pattern with higher expression observed in 8 out of 13 endometrial tumor tissues studied over normal tissues." (PMID 16188033, 2005). "Endometrial tumors showed increased expression of MUC1, MUC5B and MUC8 over normal tissues." (PMID 16188033, 2005).
endometriosis (2 papers, 2020 to 2025). The growth of functional endometrial tissue in anatomic sites outside the uterine body. "Future studies will characterize the biological functions of MUC5B+ epithelial cells in endometriosis pathogenesis." (PMID 40757199, 2025). "Our study reveals a fundamental reorganization of the epithelial compartment in endometriosis, characterized by an overall decrease in epithelial cells, contrasting with a specific expansion of the MUC5B+ epithelial subpopulation." (PMID 40757199, 2025). "Clinical validation experiments identified the MUC5B+ epithelial cell subtype as potentially the most critical factor in early endometriosis diagnosis." (PMID 40757199, 2025). "By integrating single-cell and bulk transcriptomics, we identified MUC5B+ epithelial cells and dStromal-late mesenchymal cells as dual drivers of fibrosis and inflammation in endometriosis." (PMID 40757199, 2025). "Our findings revealed that MUC5B+ epithelial cells may serve as the top factor for the diagnosis of endometriosis." (PMID 40757199, 2025). "Repeated genes associated with P-phase (ACTB, ANXA4, BPIFB1, EPHX1, MUC5B, PRDX2, and VIM) could indicate stronger genetic causes associated with pathophysiology of endometriosis." (PMID 32474803, 2020). "Notably, MUC5B+ epithelial cells displayed the largest contribution to diagnosing endometriosis." (PMID 40757199, 2025). "It revealed significantly elevated expression of MUC5B (p = 8.44E-06) and TFF3 (p = 6.41E-06) in endometriosis tissues compared to control tissues, consistent with our prior analytical findings." (PMID 40757199, 2025). "Our IHC analysis identified MUC5B and TFF3 as specifically overexpressed in endometriosis." (PMID 40757199, 2025).
HIV-1 infection (2 papers, 2006 to 2018). The type species of lentivirus and the etiologic agent of acquired immunodeficiency syndrome (AIDS). "The result revealed that after a 30 min incubation period during which the mixtures three separate mixtures (HIV-1 plus crude saliva), (HIV-1 plus MUC5B) and (HIV-1 plus MUC7) were incubated with the CD4+ CEM SS cells, no HIV-1 infection of these cells was observed." (PMID 17125499, 2006).
intestinal cancer (2 papers, 2019 to 2020). "In order to identify the regulatory regions involved in MUC5B transcription, the MUC5B promoter region in three intestinal cancer cell lines has been sequenced and analyzed by Van Seuningen and collaborators." (PMID 31309122, 2019). "Overexpression of MUC5B gene has been found in some subtypes of gastric and intestinal cancer, but the molecular mechanisms remain unknown." (PMID 32695780, 2020).
metastatic disease (2 papers, 2022 to 2025). "Interestingly, tumor cells harboring KRAS G12V upregulate several genes associated with more aggressive or metastatic tumors, including COL1A1, VIM and MUC5B 42–44." (PMID 35995947, 2022). "Targeting MUC5B could offer new opportunities for improving the diagnosis, treatment, and prognosis of LUAD patients, particularly those with advanced metastatic disease." (PMID 41409294, 2025).
nasal polyp (2 papers, 2020). "Among the mucin family members, the expressions of MUC1, MUC2, MUC4, MUC5AC, and MUC5B have been detected in the human nasal polyp and middle ear epithelial cells." (PMID 32054887, 2020). "Some studies investigated the pattern of expression of mucin in healthy nasal tissues and nasal polyps, which found that overexpressions of MUC1, MUC4, MUC5AC, and MUC5B are in nasal polyps than in healthy nasal tissues." (PMID 32812123, 2020). "Compared with normal nasal mucosa, the expression of MUC3 and MUC6 in nasal polyps is downregulated, the expression of MUC2 and muc8 in nasal polyps is upregulated, the expression of MUC5AC and MUC5B in CRS is upregulated, and the expression of MUC5AC in nasal polyps far exceeded MUC1 and MUC2." (PMID 32812123, 2020).
non-small cell lung carcinoma (2 papers, 2015 to 2023). A group of at least three distinct histological types of lung cancer, including non-small cell squamous cell carcinoma, adenocarcinoma, and large cell carcinoma. "Moreover, in non-small cell lung cancer, MUC5B expression is significantly associated with poorer differentiation, pathological stage, and poor prognosis." (PMID 36831639, 2023).
oral disease (2 papers, 2022 to 2024). "Thus, salivary hypofunction and/or hyposalivation causes a decrease in MUC5B levels and other proteins, causing dysbiosis and oral diseases." (PMID 38999930, 2024). "MUC5B influences the composition of the oral microbiota, avoiding the harmful effects of opportunistic pathogens, such as C. albicans; for this reason, these pathogens remain in the oral cavity without causing oral diseases." (PMID 38999930, 2024). "Upregulation of the building blocks of secretory airway mucus, gel forming mucin 5AC and mucin 5B (MUC5AC, MUC5B), is a common symptom of both respiratory and oral disease state." (PMID 36146663, 2022).
otitis media (2 papers, 2012 to 2022). Inflammation of the anatomical structures of the middle ear, which is most often caused by an infectious process. "We also investigated the expression levels of Muc5a, Muc5b, Tgf-β1 and Tlr2 genes which have been reported to be involved in the development of otitis media and inflammation." (PMID 22539951, 2012). "Moreover, upregulation of Muc5ac and Muc5b in Galnt2 mutant mice resulted in increased middle ear effusion and decreased mucociliary clearance, thereby preventing otitis media." (PMID 36874359, 2022).
pneumoconiosis (2 papers, 2022 to 2024). An occupational lung disorder caused by inhalation of dust particles. "This study investigates the correlations of mucin 5B (MUC5B) rs2672794, rs2075854, and rs868903 polymorphisms and MUC5B expression level with the risk of the onset of coal workers’ pneumoconiosis (CWP)." (PMID 39969351, 2024). "A study conducted on a Chinese population shows that MUC5B rs2672794 gene polymorphism is in direct association with coal miner’s pneumoconiosis, thus MUC5B rs2672794 CC genotype could increase the risk of developing pneumoconiosis." (PMID 36672608, 2022).
polyp (2 papers, 2022 to 2023). A usually exophytic mass attached to the underlying tissue by a broad base or a thin stalk. "It is worth mentioning that among the seven mucin (MUC) proteins, MUC5A and MUC5B exhibited a significant increase in gallstone bile compared to polyp bile." (PMID 38111640, 2023). "We did, however, observe an overrepresentation of mucus secretory (goblet) cells with high expression of both MUC5AC and MUC5B in polyp epithelium, consistent with the mucus metaplasia observed in patients with CRSwNP." (PMID 35608904, 2022).